U3 (Small nucleolar RNA U3 )
Synonyms: LOC124904984
Gene: Small nucleolar RNA gene on chromosome 20 (16,982,831 to 16,983,033, reverse strand). Ensembl gene ENSG00000212165.
Gene Ontology:
Biological process: RNA processing
Cellular component: nucleolus
Homologues: Orthologues: chimpanzee U3 (97% identical), macaque U3 (93% identical), pig U3 (57% identical), dog U3 (49% identical). Paralogues in human: U3 (83% identical), SNORD3P1 (81% identical), U3 (81% identical), SNORD3E (78% identical), U3 (78% identical), SNORD3D (78% identical), SNORD3G (77% identical), U3 (77% identical), U3 (76% identical), U3 (75% identical), U3 (74% identical), SNORD3H (73% identical), and 12 more.